PGR (progesterone receptor)
Diseases named in the same sentence as PGR in open-access papers (continued):
Sharing a sentence is not in itself a finding about the gene and the disease.
triple-negative breast carcinoma (continued). "Triple negative breast cancers (TNBC) are a group of heterogeneous cancers characterized by their lack of estrogen receptor (ER), progesterone receptor (PR), and ErbB2/HER2/Neu." (PMID 32349331, 2020). "Triple-negative breast cancer (TNBC), defined as not expressing the estrogen receptor (ER), the progesterone receptor (PR), and human epidermal growth factor receptor 2 (HER2), accounts for nearly one fifth of all BCs." (PMID 33505908, 2020). "For the last, basal-type are also known as triple negative breast cancer (TNBC), because these tumors are estrogen receptor negative (ER-), progesterone receptor negative (PR-), as well as HER-2 negative." (PMID 32517101, 2020). "Triple-negative breast cancer (TNBC), lacking estrogen receptor (ER), progesterone receptor (PR), and human epidermal growth factor receptor 2 (HER2) amplification, represents approximately 15-20% of primary breast cancers." (PMID 32929364, 2020). "Triple negative breast cancer (TNBC) which lack of estrogen receptor (ER), progesterone receptor (PR) and human epidermal growth factor receptor type 2 (HER2) has the poorest survival outcome due to its aggressiveness and lack of therapeutic target." (PMID 32754442, 2020). "Triple-negative breast cancer (TNBC) represents one of the subtypes described in recent years, which does not express estrogen receptor (ER), progesterone receptor (PR) or human epidermal growth factor receptor 2 (HER2)." (PMID 33344259, 2020). "Approximately 15–20% of all breast cancers are triple-negative breast cancer (TNBC) due to the lack of expression of three proteins: estrogen receptor (ER), progesterone receptor (PR), and HER2." (PMID 31220107, 2019). "Triple-negative breast cancer (TNBC) is defined as the negative immunohistochemical test results of estrogen receptor (ER), progesterone receptor (PR), and human epidermal growth factor receptor-2 (Her-2)." (PMID 31123166, 2019). "Triple-negative breast cancer (TNBC) is characterized by a lack of the estrogen receptor (ER), progesterone receptor (PgR), and human epidermal growth factor receptor 2 (Her2) expression and/or amplification." (PMID 31540486, 2019). "Triple-negative breast cancer (TNBC) rep­resents a diverse group of cancers that are characterized by lack of expression of the estrogen receptor (ER), progesterone receptor (PR), and human epidermal growth factor receptor 2 (HER2) amplification." (PMID 30909550, 2019). "Triple-negative breast cancer (TNBC) was characterized by the lack of estrogen receptor (ER), progesterone receptor (PR), and HER2." (PMID 31023384, 2019). "Triple-negative breast cancer (TNBC), characterized by the lack of expression of the estrogen receptor (ER), the progesterone receptor (PR), and the human epidermal growth factor receptor 2 (HER2), is a heterogeneous subtype of epithelial breast tumor." (PMID 30823477, 2019). "Triple-negative breast cancer (TNBC) is a subtype of breast cancer that based on immunohistochemistry features of estrogen receptor (ER) negative, progesterone receptor (PR) negative and human epidermal growth factor receptor 2 (HER2) negative." (PMID 32010177, 2019). "Triple negative breast cancer (TNBC) does not express the estrogen receptor, progesterone receptor, or human epidermal growth factor receptor 2, resulting in limited treatment options." (PMID 34322598, 2019). "Triple-negative breast cancers (TNBC) constitute a heterogeneous group of breast cancers, defined histologically by the lack of expression of the estrogen receptor (ER), progesterone receptor (PR), and the human epidermal growth factor receptor 2 (HER2)." (PMID 31312514, 2019). "Triple negative breast cancer (TNBC) is clinically defined based on the absence of the estrogen and progesterone receptor, and HER2 overexpression." (PMID 30087365, 2018).
triple-negative breast carcinoma (continued). "Triple-negative breast cancer (TNBC) is one subtype that does not express the estrogen receptor (ER) and progesterone receptor (PR) or overexpress the human epidermal growth factor-2 (HER-2)." (PMID 30202040, 2018). "Triple-negative breast cancer (TNBC) does not express estrogen receptor, progesterone receptor, and human epidermal growth factor receptor 2 and is characterized by its aggressive nature, lack of targets for targeted therapies, and early peak of recurrence." (PMID 30363988, 2018). "Triple-negative breast cancers (TNBC), which constitute about 20% of all breast cancers, lack estrogen receptor (ER) and progesterone receptor (PR) expression and do not show gene amplification of the human epidermal growth factor receptor 2 (HER2)." (PMID 30513833, 2018). "Triple-negative breast cancer (TNBC), is a heterogeneous disease characterised by absence of expression of the estrogen receptor (ER), progesterone receptor (PR) and lack of amplification of human epidermal growth factor receptor 2 (HER2)." (PMID 29644001, 2018). "Triple-negative breast cancer (TNBC) is defined by the lack of Ostrogen receptor (ER-), Progesterone receptor (PgR-), and HER2/neu receptor (HER2-)." (PMID 30458011, 2018). "One particular subtype of ERα-negative breast cancer is triple-negative breast cancer (TNBC) characterized by the lack of ERα and progesterone receptor expression and the absence of Her-2 overexpression." (PMID 30687231, 2018). "Triple-negative breast cancer (TNBC), is a heterogeneous disease characterised by negative expression of the estrogen receptor (ER), progesterone receptor (PR) and lack of overexpression of the human epidermal growth factor receptor 2 (HER2)." (PMID 29644001, 2018). "Triple-negative breast cancer (TNBC) that does not express estrogen receptor (ER), progesterone receptor (PR), and HER-2/neu is the most aggressive sub-type of breast cancer." (PMID 30185799, 2018). "Triple-negative breast cancer (TNBC) is characterized by the lack of estrogen receptor, progesterone receptor and human epidermal growth factor receptor-2 (HER-2) expression." (PMID 29875927, 2018). "Triple negative breast cancer (TNBC) comprises a heterogeneous group of tumors defined as a basal-like subtype lacking estrogen receptor alpha (ESR1), progesterone receptor (PGR), and human epidermal growth factor receptor 2 (ERBB2)." (PMID 30123188, 2018). "Triple-negative breast cancer (TNBC) is the most challenging subtype to treat due to the lack of estrogen receptor, progesterone receptor, and HER2 expression, which excludes the usage of directed targeted therapy against them." (PMID 30227653, 2018). "Triple-negative breast cancer (TNBC) is defined by the lack of an estrogen receptor (ER), a progesterone receptor (PR), and a human epidermal growth factor receptor-2 (HER-2)." (PMID 29423090, 2018). "The triple-negative breast cancer (TNBC) subtype is characterized as being negative for the estrogen receptor 1 (ESR1), progesterone receptor (PGR), and human epidermal growth factor receptor type 2 (HER2)." (PMID 30050079, 2018). "Triple-negative breast cancer (TNBC) is a unique subset of human breast cancer that is characterized by negative estrogen receptor (ER), progesterone receptor (PR) and human epidermal growth factor receptor 2 (HER2) status." (PMID 30577812, 2018). "Tumours that are ER negative, progesterone receptor negative and HER2 negative, also known as triple-negative breast cancers (TNBCs), usually grow the fastest and are more metastatic." (PMID 28067227, 2017). "A sub-type of BC, namely triple negative breast cancer (TNBC) is negative for estrogen and progesterone receptor (ER, PR) and HER-2/neu." (PMID 29088794, 2017). "Further analysis revealed the cancer specimen was negative for estrogen receptor (ER), progesterone receptor (PR), and human epidermal growth factor receptor 2 (HER-2), indicating that the malignancy was triple-negative breast cancer." (PMID 29381961, 2017).
triple-negative breast carcinoma (continued). "Triple negative breast cancer (TNBC) is defined as any breast cancer that does not express the genes for estrogen receptor (ER), progesterone receptor (PR) and human epidermal growth factor receptor 2 (HER-2)." (PMID 29348858, 2017). "Triple negative breast cancer (TNBC) accounts for approximately 15% of all breast cancers diagnosed and is defined by the absence of estrogen receptor alpha (ERα), progesterone receptor (PR), and human epidermal growth factor receptor 2 (HER2) amplification." (PMID 29228549, 2017). "Triple-negative breast cancer (TNBC) is characterized by a lack of estrogen and progesterone receptor expression (ESR and PGR, respectively) and an absence of human epithelial growth factor receptor (ERBB2) amplification." (PMID 29115931, 2017). "Another type of breast cancer is negative for the ERα, progesterone receptor (PR) and HER2 called triple negative breast cancer (TNBC)." (PMID 28474005, 2017). "Human triple-negative breast cancer (TNBC), which accounts for approximately 10–20% of all breast tumors, refers to forms that do not express estrogen receptor (ER), progesterone receptor (PR) and human epidermal growth factor receptor 2 (HER2)." (PMID 28423652, 2017). "Triple-negative breast cancer (TNBC) is an aggressive subgroup of human breast cancer, which is characterized as estrogen receptor (ER) negative, progesterone receptor (PR) negative, and human epidermal growth factor receptor 2 (HER2) negative." (PMID 29069872, 2017). "Triple negative breast cancer (TNBC) is a subtype of tumors that do not clinically express human epidermal growth factor receptor 2 (HER-2), progesterone receptor (PR), or estrogen receptor (ER)." (PMID 28740515, 2017). "Triple negative breast cancer (TNBC) accounts for 15–20% of all breast cancers and is defined by a lack of estrogen receptor (ER), progesterone receptor (PR), and human epidermal growth factor receptor 2 (HER2)." (PMID 29258605, 2017). "Triple-negative breast cancer (TNBC) is characterized by a lack of expression of estrogen receptor (ER), progesterone receptor (PR), and human epidermal growth factor receptor 2 (HER2) and represents up to 20% of all breast cancers." (PMID 28107186, 2017). "Triple-negative breast cancer (TNBC), which is characterized by the lack of estrogen/progesterone-receptor (ER/PR) and human epidermal growth factor receptor-2 (HER-2), accounts for 15 to 20% of all BC cases." (PMID 28938657, 2017). "Triple negative breast cancer (TNBC) is a diagnosis by exclusion corresponding to tumors that are immunohistochemically (IHC) negative for estrogen receptor (ER), progesterone receptor (PgR) and HER2 protein overexpression." (PMID 27685159, 2016). "Triple-negative breast cancer (TNBC) is defined by a lack of expression of estrogen receptor (ER), progesterone receptor (PgR) and overexpression of human epidermal growth factor receptor-2 (HER-2)." (PMID 27604655, 2016). "Triple-negative breast cancer (TNBC) is a heterogeneous disease characterized by the absence of ER, PgR and HER2, and up to six distinct biological subgroups are reported." (PMID 27448975, 2016). "Triple negative breast cancer (TNBC) is defined by the absence of estrogen receptor (ER), progesterone receptor (PR), human epidermal growth factor receptor 2 (HER2) and accounts for 12–15 % of all invasive breast cancer." (PMID 27553291, 2016). "One of these subtypes is triple-negative breast cancer (TNBC), which is negative in estrogen receptor (ER) and progesterone receptor (PR) and also negative in human epidermal growth factor receptor 2 (HER2) overexpression." (PMID 26727947, 2016). "Triple-negative breast cancer (TNBC) is a heterogeneous disease in which the tumors do not express estrogen receptor (ER), progesterone receptor (PgR) or human epidermal growth factor receptor 2 (HER2)." (PMID 27448975, 2016).
triple-negative breast carcinoma (continued). "Triple negative breast cancer (TNBC) is typified by lack of expression of estrogen receptor (ER), progesterone receptor (PR), and human epidermal growth factor receptor-2 (HER-2)." (PMID 27480353, 2016). "Triple-negative breast cancer (TNBC) refers to tumors that do not express the genes for estrogen receptor (ER), progesterone receptor (PR) and Her2/neu." (PMID 27563827, 2016). "Triple Negative Breast Cancer (TNBC) is defined by a lack of estrogen and progesterone receptor gene expression and by the absence of overexpression on HER2." (PMID 27770782, 2016). "Triple-negative breast cancer (TNBC) is defined by the lack of immunohistochemical expression of the estrogen receptor (ER) and progesterone receptor (PR) and the absence of human epidermal growth factor receptor 2 (HER-2) overexpression." (PMID 27626685, 2016). "Triple-negative breast cancer (TNBC) is a subtype of breast cancer that is lacking the expression ofestrogen receptor (ER), progesterone receptor (PR) and HER2 (ERBB2)." (PMID 26681397, 2015). "Triple-negative breast cancers (TNBC) is a malignant subtype that fails to express the estrogen receptor (ER), progesterone receptor (PR), and human epidermal growth factor receptor 2 (HER2), representing 10–20% of all breast cancer cases." (PMID 26528725, 2015). "Triple-negative breast cancer (TNBC) is defined by lack of expression of estrogen receptor (ER), progesterone receptor (PGR) and human epidermal growth factor receptor 2 (HER-2)." (PMID 26160845, 2015). "Triple Negative Breast Cancer (TNBC), which accounts for 12–24% of all breast carcinomas, is defined by the lack of expression of estrogen, progesterone receptors (ER, PgR) and HER2." (PMID 26540293, 2015). "Triple-negative breast cancer (TNBC) accounts for about 15% of breast cancer cases and is characterized by absence of estrogen receptor (ER), progesterone receptor (PR) and HER2 receptors." (PMID 25153718, 2014). "The lesion exhibited squamous features with a histological grade of three and was negative for the expression of ER, PgR and HER2; the tumor was a triple-negative breast cancer." (PMID 24520287, 2014). "Triple-negative breast cancer (TNBC) is characterized by lack of expression of estrogen receptor (ER) and progesterone receptor (PgR) and overexpression of human epidermal growth factor receptor 2 (Her-2)." (PMID 25389442, 2014). "Triple-negative breast cancer (TNBC) refers to any breast cancer that does not express the genes for estrogen receptor (ER), progesterone receptor (PR) and Her2/neu." (PMID 24914410, 2014). "In particular, the triple-negative breast cancer (TNBC), characterized by a receptor negative pattern (ER/PgR/HER2–negative) and poor prognosis, can represent one of the most relevant clinical and public health priority in terms of observational research." (PMID 25413873, 2014). "Triple negative breast cancer (TNBC) is characterized by lack of expression of both estrogen and progesterone receptor as well as lack of overexpression or amplification of HER2." (PMID 25033833, 2014). "Triple negative breast cancer (TNBC) and often basal-like cancers are defined as negative for estrogen receptor, progesterone receptor and Her2 gene expression." (PMID 25100201, 2014). "Triple-negative breast cancer (TNBC) is characterized by a lack of expression of estrogen receptor (ER), progesterone receptor (PR) and ErbB-2/human epidermal growth factor receptor 2 (HER2)." (PMID 25104095, 2014). "On the other hand, these tumor cells were completely negative for hormone receptors (ER and PgR) and HER2, manifesting as triple-negative breast cancer." (PMID 23651662, 2013). "Triple-negative breast cancer (TNBC) is defined as a subgroup of breast carcinomas that are negative for expression of estrogen receptor (ER), progesterone receptor (PR) and human epidermal growth factor receptor-2(HER2)." (PMID 23555923, 2013).
triple-negative breast carcinoma (continued). "There was a statistically significant higher frequency of ER−, PgR− and HER2-receptor negative patients [triple-negative breast cancer (TNBC)] that succumbed to the disease within 44 months after treatment, compared to ER+, PR+ and HER2− patients." (PMID 24649267, 2013). "Triple negative breast cancer (TNBC) is defined clinically by the absence of estrogen receptor (ER), progesterone receptor (PgR), and HER2/neu overexpression and encompasses a molecularly diverse group of diseases." (PMID 23983689, 2013). "Triple Negative Breast Cancer (TNBC) is a heterogeneous disease that based on immunohistochemistry (IHC) is estrogen receptor (ER) negative, progesterone receptor (PR) negative and human epidermal growth factor receptor 2 (HER2) negative." (PMID 25285241, 2013). "Triple-negative breast cancer (TNBC) is characterized by a lack of receptor expression of the estrogen receptor (ER), progesterone receptor (PR) and human epidermal growth factor receptor 2 (HER2)." (PMID 24130769, 2013). "Systemic treatment for triple negative breast cancer (TNBC: negative for the expression of estrogen receptor and progesterone receptor and HER2 amplification) has been limited to chemotherapy options." (PMID 23983689, 2013). "Triple-negative breast cancer (TNBC), defined by the absence of an estrogen receptor, progesterone receptor, and human epidermal growth factor receptor 2 expression, is associated with an early recurrence of disease and poor outcome." (PMID 24130769, 2013). "Triple-negative breast cancer (TNBC) is defined by the lack of the expression of estrogen receptor (ER), progesterone receptor (PR) and human epidermal growth factor receptor 2 (HER2)." (PMID 23555923, 2013). "Triple-negative breast cancers (TNBC) are defined by the lack of expression of the estrogen receptor (ER), progesterone receptor (PR) and human epidermal growth factor receptor 2 (HER2)." (PMID 24063698, 2013). "Triple-negative breast cancer (TNBC) is characterized by lacking of expression of both estrogen receptor (ER) and progesterone receptor (PR) as well as HER2." (PMID 23046633, 2012). "Triple-negative breast cancer (TNBC) is a heterogeneous subgroup of breast cancer characterized by the lack of estrogen receptor (ER), progesterone receptor (PR) and the human epidermal growth factor receptor 2 (HER2) expressions." (PMID 23009686, 2012). "Triple-negative breast cancer (TNBC) is characterized by a lack of receptor expression of estrogen receptor (ER) and progesterone receptor (PgR) and lack of gene expression for human epidermal growth factor receptor 2 (HER2)." (PMID 22452810, 2012). "Triple negative breast cancer (TNBC) is defined by the absence of estrogen receptor (ER), progesterone receptor (PR), and HER-2 Overexpression." (PMID 22295242, 2012). "The triple-negative breast cancers (TNBC)—so called because they are negative for estrogen receptor (ER), progesterone receptor (PgR), and HER2 —include a large proportion of basal-like tumors." (PMID 22763464, 2012). "Triple negative breast cancer (TNBC) is defined by a lack of expression of both estrogen (ER) and progesteron (PgR) receptors as well as human epidermal growth factor receptor 2 (HER2)." (PMID 22933934, 2011). "Triple-negative breast cancer (TNBC), a subtype of breast cancer that is oestrogen receptor (ER) negative, progesterone receptor (PR) negative, and human epidermal growth factor receptor 2 (HER2) negative, has a poor prognosis." (PMID 20551954, 2010). "Triple-negative breast cancer (TNBC), characterized by the absence of estrogen receptor (ER), progesterone receptor (PR), and human epidermal growth factor receptor 2 (HER2) expression, remains clinically challenging due to the lack of effective targeted therapies." (PMID 41518487, 2026).